NNT-AS1 (NNT antisense RNA 1)
Synonyms: RP11-159F24.1
Gene: Long non-coding RNA gene on chromosome 5 (43,571,594 to 43,603,230, reverse strand). Ensembl gene ENSG00000248092.
Diseases named in the same sentence as NNT-AS1 in open-access papers:
NNT-AS1 is named in the same sentence as 8 diseases in open-access papers, as found by Europe PMC text mining. Sharing a sentence is not in itself a finding about the gene and the disease. The quoted sentences say what the papers report.
hepatocellular carcinoma (2 papers, 2020 to 2023). A malignant tumor that arises from hepatocytes. "Nicotinamide nucleotide transhydrogenase-antisense RNA1 (NNT-AS1) is a long noncoding RNA (lncRNA) that has been shown to be overexpressed in hepatocellular carcinoma (HCC)." (PMID 33426064, 2020).
lung cancer (2 papers, 2021 to 2023). A malignant neoplasm involving the lung. "For example, NNT-AS1 has been shown to function as the oncogene role in cancer, which was elevated in non‐small cell lung cancer (NSCLC) and tightly correlated with the tumorigenic phenotypes and unfavorable prognosis." (PMID 38036719, 2023). "Some LncRNAs including HOTAIR, MALAT1, NEAT1, and NNT‐AS1 have been involved in cisplatin resistance, through WNT and/or MAPK/Slug intracellular signaling pathways, as well as promoting malignancy in solid lung tumors, and lung cancer cell lines." (PMID 33433063, 2021).
bladder cancer (1 paper, 2019). "To investigate the mechanisms by which NNT-AS1 promotes the malignant behaviors of bladder cancer cells, we first analyzed the subcellular localization of NNT-AS1 in these cells." (PMID 31848324, 2019).
prostate carcinoma (1 paper, 2023). A carcinoma that arises from epithelial cells of the prostate gland. "In addition, DDIT4 expression could be induced by nicotinamide nucleotide transhydrogenase antisense RNA 1 (NNT-AS1)/miR-496 axis in prostate cancer and played a carcinogenic role in proliferation and migration." (PMID 36768316, 2023).
cancer (4 papers, 2019 to 2023). A tumor composed of atypical neoplastic, often pleomorphic cells that invade other tissues. "In this review, we summarize the abnormal expression of NNT-AS1 in a variety of neoplastic diseases and its diagnostic and prognostic value, and we explain the mechanism by which NNT-AS1 regulates cancer progression by competing with miRNAs." (PMID 33113895, 2020). "The long noncoding RNA nicotinamide nucleotide transhydrogenase antisense RNA 1 (NNT-AS1) is a key malignancy regulator in a variety of human cancers." (PMID 31848324, 2019). "An lncRNA called nicotinamide nucleotide transhydrogenase antisense RNA 1 (NNT-AS1) is abnormally expressed in a variety of human cancers and functions as a key regulator of cancer progression." (PMID 31848324, 2019). "NNT-AS1 overexpression has been reported in several studies, but some studies have found that NNT-AS1 expression is decreased in cancer." (PMID 33426064, 2020).
neoplastic diseases (2 papers, 2017 to 2020). "Nicotinamide nucleotide transhydrogenase-antisense 1 (NNT-AS1), which is a newly-discovered long non-coding RNA (lncRNA), has been found to be dysregulated in a variety of neoplastic diseases." (PMID 33113895, 2020).
NNT-AS1 also shares sentences with these, for which no sentence is quoted: breast cancer (2 papers); gastric cancer (2).